TNF (tumor necrosis factor)
Diseases named in the same sentence as TNF in open-access papers (continued):
Sharing a sentence is not in itself a finding about the gene and the disease.
Autoimmunity (continued). "Our study showed that TNF-α signaling was an essential feature of PNS autoimmunity, since TNF-α expression limitation protected against PIN." (PMID 35893792, 2022). "Immunomodulators such as tumour necrosis factor (TNF) inhibitors are used to treat autoimmune conditions by reducing the magnitude of the innate immune response." (PMID 36159650, 2022). "Streptococcus induces expression of the pro‐inflammatory cytokines TNF‐α, IL‐6, and IFN‐γ, which are associated with autoimmunity." (PMID 33970540, 2021). "Adalimumab is a monoclonal antibody targeting tumour necrosis factor-alpha (TNF-alpha) and is used for the treatment of numerous autoimmune conditions." (PMID 34336477, 2021). "IL-17 is a pro-inflammatory cytokine secreted by T helper 17 cells that act with other cytokines such as IL-1, TNF-α, and IL-6 to induce inflammatory diseases and play an important role in the development of autoimmunity." (PMID 34086720, 2021). "More than 120 cases with lichenoid skin reactions to anti-TNF-α treatment are described (AE type γ, autoimmunity by immunomodulation)." (PMID 33802483, 2021). "In NZB/W F1 mice, the delayed onset of autoimmunity in the presence of neutralizing α-IL-10 was suspected to be due to an up-regulation of endogenous TNF-α." (PMID 33572870, 2021). "For example, Anakinra (IL-1R antagonist), and Adalimumab (mAbs anti-TNF-α) can be used to treat autoimmune conditions." (PMID 34434197, 2021). "These include antibody-mediated CNS disorders following herpes simplex virus encephalitis or occurring in a post-transplant setting, and neurological autoimmunity triggered by TNFα inhibitors or immune checkpoint inhibitors for cancer treatment." (PMID 34305787, 2021). "A few cases of new onset alopecia areata/totalis and vitiligo have been described in patients using anti-TNF-α therapy (AE type γ, autoimmunity by immunomodulation)." (PMID 33802483, 2021). "For many years TNF was mainly considered a proinflammatory cytokine with its role in host defense, but also with detrimental effects on autoimmunity." (PMID 34054827, 2021). "The tumor necrosis factor α (TNFα) has been employed as a promising reagent in treating autoimmunity and cancer diseases." (PMID 34199525, 2021). "It is also reported in about 0.5% of IBD patients treated with TNF-α inhibitors (AE type γ, autoimmunity by immunomodulation)." (PMID 33802483, 2021). "Although the pro-inflammatory roles of TNF and IL-12 are well-established, the immunosuppressive role of IL-6 was overlooked in autoimmunity." (PMID 34215755, 2021). "Several factors that play important roles in autoimmunity are present in TA and CD, such as lymphocyte subtype and proinflammatory cytokines (IFNγ, TNFα, IL-6, IL-17, IL-18)." (PMID 33628228, 2021). "Another piece of evidence is the significant increment in dsDNA Ab titers after therapy in patients treated with either IFX, ADA, or ETN, suggesting that autoimmunity was enhanced by inhibiting the TNF pathway." (PMID 33315881, 2020). "Adult men with autoimmune conditions are commonly prescribed anti-tumor necrosis factor (anti-TNF) agents; however, there is a paucity of quality evidence as to their effect on male fertility (e.g. semen parameters and sperm quality)." (PMID 32718310, 2020). "Tumor Necrosis Factor alpha (TNFα) is a central mediator in the immunologic processes of infection control, autoimmunity, allergic disease, as well as the anti-neoplastic activity for which it was named." (PMID 33324405, 2020). "Treatment with OA also reduced the indices of inflammation and autoimmunity in colon tissues, (i.e., increased TNFα, IL-1β, IL-23, IL-17A, and KC; and reduced IL-13, IL-33, and IL-25)." (PMID 33246492, 2020). "Anti -TNF agents are commonly prescribed to young adult men with autoimmune conditions on a long-term basis." (PMID 32718310, 2020). "TNF-α is considered to participate in the process of pathology like chronic inflammation, autoimmunity as well as malignant disease." (PMID 32194791, 2020).
Autoimmunity (continued). "Since TNFα is an important mediator in infections and tumors, a series of biological agents targeted to TNFα has been developed for the treatment of cancer and autoimmunity." (PMID 31266509, 2019). "Some of the other models present in silico clinical trials in phenomenological or more mechanistic target terms and address anti-TNF agents, yet other models address the role of mimicry in autoimmunity." (PMID 32117197, 2019). "The prophylactic TNF blockade strategy is clinically feasible since excellent TNF inhibitors have been approved for the treatment of autoimmunity and are used for the immune-related serious adverse events in immunotherapy." (PMID 31309173, 2019). "In our degranulation assay, priming with C5a instead of TNF-α resulted in a 10-fold increased release of the ANCA antigens PR3 and MPO, implying an increased exposure and thereby possibly an increased risk of autoimmunity in C5a-driven inflammation." (PMID 31216309, 2019). "Absence of TNF-α is associated with progression to severe TB disease, as seen following treatment with anti-TNF monoclonal antibodies for autoimmune conditions." (PMID 31294001, 2019). "Interferon (IFN)-γ signaling and tumor necrosis factor (TNF) are highly implicated in ITP pathogenesis and provides a link between autoimmunity, inflammation, and bone marrow failure." (PMID 31998632, 2019). "The DUB OTULIN is an essential negative regulator of inflammation and prevention of autoimmunity involving the TNF pathway." (PMID 30755793, 2019). "Our results indicate that leptin is required for human immune homeostasis and contributes to autoimmunity in a TNFα-dependent manner." (PMID 31822667, 2019). "Despite the untoward effect of TNF in the development of autoimmunity, it has also been demonstrated that TNF is sometimes needed to inhibit or control autoimmunity." (PMID 29751683, 2018). "It is reported that MRP8 also acts as an endogenous activator of TLR4 and promotes inflammatory processes in infection and autoimmunity by amplifying TNF-α release in response to LPS." (PMID 29902248, 2018). "Following this initial success several other anti-TNF-α drugs were tested in the clinic and anti-TNF-α treatment is now a fundamental step in the treatment of autoimmunity." (PMID 29541073, 2018). "TNF-α is produced at low levels in the tumor microenvironment by tumor or stromal cells, or probably both, and perpetuates chronic inflammation and autoimmunity together with IL-6, a key cytokine linking chronic inflammation to cancer." (PMID 28030810, 2017). "Proinflammatory agents (e.g., IL-1, IL-6, and TNF-α) appear to have a substantial role in the control of autoimmunity, and overproduction of cytokines can provoke some autoimmune disorders." (PMID 28611508, 2017). "As a central event of inflammation and immunity, TNFα-induced NF-κB activation must be tightly controlled to avoid inflammatory diseases, autoimmunity and cancers." (PMID 29255244, 2017). "TNF-α is the main proinflammatory cytokine that exacerbated myocarditis through excessive autoimmunity." (PMID 27766098, 2016). "Members of the Tumor Necrosis Factor (TNF) receptor family have been shown to stimulate DC maturation or modulate peripheral tolerance in autoimmunity by upregulation of IDO1." (PMID 26881431, 2016). "Th17 cells mainly regulated by Rorc produce IL-17, TNF-α and IL-6 to promote the development of autoimmunity and allergic reactions." (PMID 25873156, 2015). "This would be consistent with current clinical practices such as the use of anti-TNF therapy in the management of a range of autoimmune disorders." (PMID 26553024, 2015). "TNF-α (tumor necrosis factor-alpha) is a cytokine that plays an important role in the regulations of immune functions, cell proliferation and differentiation, apoptosis due to autoimmunity, coagulation, adipocyte, lipid and glucose metabolism." (PMID 24891849, 2014).
Autoimmunity (continued). "Prospective, randomized controlled studies using anti-inflammatory agents such as TNF-α or steroids would be performed in a large population in the patients with autoimmune pathology if it can be confirmed by the autoimmunity screening." (PMID 25330336, 2014). "On another note, increased estrogen levels during pregnancy make adenohypophysis cells, particularly the lactotroph cells, more vulnerable to apoptosis due to autoimmunity as a result of elevated expression of the TNF-α gene in rats." (PMID 24891849, 2014). "Anti-inflammatory treatments have improved the prognoses of many patients in chronic inflammatory conditions, the most notable example being biologics such as tumor necrosis factor (TNF)-inhibitors in RA and other autoimmune conditions." (PMID 24194733, 2013). "It has been reported that cytokines such as IFN-γ and TNF-α can initiate apoptosis and thus lead to melanocyte death in the context of autoimmunity." (PMID 23284977, 2012). "For the first time we report that generalized vitiligo has significantly higher TNF-α transcript and protein levels as compared to localized vitiligo patients which indicate involvement of autoimmunity in precipitation of generalized vitiligo." (PMID 23284977, 2012). "TNF-α in synergy with IFN-γ (which was present in the 4 week transcriptome network) is known to be important in inducing autoimmunity in the developing immune system." (PMID 23071669, 2012). "Treatment with TNF-α appears to offer a highly targeted strategy to destroy autoreactive activated T cells and interrupt the pathogenesis of autoimmunity." (PMID 22685592, 2012). "Recently the development of autoimmunity in patients treated with TNF-alpha antagonists has stimulated interest in the possible role of TNF in SLE." (PMID 18437207, 2008). "Additionally, MS patients with a family history of autoimmunity have a lower age at onset of the disease with a higher TNF-α level." (PMID 41771986, 2026). "Furthermore, inhibition of TNF-α has considerable therapeutic potential for diseases such as diabetes and autoimmune conditions." (PMID 40338229, 2025). "In addition to autoimmunity, lymphocytes’ release of pro-inflammatory cytokines such as tumor necrosis factor-α (TNF-α), IL-2, and interferon gamma contributes to OL death." (PMID 40806380, 2025). "Elevated levels of IL-6, TNF-α, and IL-1β contribute to chronic inflammation and antibody production, whereas decreased production of IL-10 may explain the failure to suppress autoimmunity in ITP." (PMID 40922302, 2025). "This case inspired us to further analyze the paradoxical immune mechanisms of TNF-α blockade that might induce autoimmunity and the pathomechanisms of HS and VKHD, revealing an interplay of TNF-α and IL-17 signaling pathways." (PMID 41142785, 2025). "Using GeneHarmony, we were able to identify TNF (alias TNF-α) and IL6 as important genes associated with all three disease groups, which might provide further insight into SjD development of autoimmunity systemically." (PMID 40650157, 2025). "However, targeted anti-interleukin therapies like Stelara (ustekinumab) or TNF-alpha blockers like Humira (adalimumab) are used to manage autoimmunity." (PMID 41424801, 2025). "Here we discuss common pathomechanisms of HS and Vogt-Koyanagi-Harada disease (VKHD) and immune mechanisms of TNF-alpha blockade that might lead to autoimmunity." (PMID 41142785, 2025). "The increased proportion of Th 17 cells promotes the secretion of pro-inflammatory factors, such as tumor necrosis factor-α (TNF-α), which are intimately involved in the inflammatory injury of the liver and the activation of autoimmunity during its transitional phase." (PMID 38404291, 2024). "Therefore, the reported triple combination of TUDCA, creatine, and CoQ10 should be further evaluated for these autoimmune conditions that are known to improve from TNF-α inhibition." (PMID 39764390, 2024).
Autoimmunity (continued). "Candida species could activate dendritic cells or macrophages, leading to IL-6, IL-10, TNF-α and anti-dsDNA production, thus perpetuating autoimmunity." (PMID 39637140, 2024). "For example, Balkwill, F demonstrated 60 that TNF-α is involved in pathological processes such as immune system maintenance and homeostasis, inflammation, host defense, chronic inflammation, and autoimmunity and that it is also involved in the development of malignant diseases." (PMID 38577592, 2024). "discussed how males often have better outcomes with tumor necrosis factor (TNF) inhibitors in autoimmune conditions, whereas females may experience more adverse effects and lower remission rates." (PMID 39555056, 2024). "TNFα mediates inflammatory processes during infection or autoimmunity." (PMID 38715090, 2024). "Cancer continued to be the most common disease targeted by drugs, followed by autoimmune conditions, and the most common targets included TNF, PD-1, CD3, CD20, HER2, FcRn, IL-23 p19 subunit, and other interleukins, and calcitonin gene-related peptide, plus an exogenous source of enzymes." (PMID 39335511, 2024). "TNF-α stimulates a number of biological responses in the liver, such as apoptosis and necroptosis of hepatocytes, inflammation and regeneration of the liver, and autoimmunity." (PMID 38313162, 2023). "TNF plays an important role in the development of liver and kidney damage, by inducing hepatocyte apoptosis and necroptosis, liver inflammation and regeneration, and autoimmunity in the liver." (PMID 37784156, 2023). "Anti-tumor necrosis factor agents are a first-line therapy for many autoimmune conditions." (PMID 37511975, 2023). "TNFα regulates inflammation and autoimmunity development, including SLE." (PMID 38164134, 2023). "As it has been proposed that TNFα and IFNα signaling pathways cross-regulate each other, EGA treatment might be beneficial by suppressing both IFNα and TNFα in autoimmunity, although this remains to be adequately determined." (PMID 38077311, 2023). "Meanwhile, another study found that TNF promotes re-sheathing in oligodendrocyte growth and suppresses autoimmunity simultaneously, by promoting tmTNF/TNFR2 simultaneously, and has a protective effect in demyelinating disease, and improve motor and cognitive symptoms in EAE mice effectively." (PMID 36389810, 2022). "MC-secreted cytokines and chemokines encoded by IL1B, TNF, CCL3, and CCL4, all of which contribute to autoimmunity and inflammation, may stimulate other cell populations expressing their homologous receptors." (PMID 36301664, 2022). "Moreover, IL-1β and TNF-α both can activate the generation of pro-inflammatory IL-6 and then contributes to the pathogenesis of various diseases, such as inflammation, autoimmunity, and malignancies." (PMID 36139256, 2022). "Additionally, the use of monoclonal antibodies, such as anti-TNF, to the immunosuppressive therapy seems to be effective in controlling autoimmunity but studies that are more robust are needed." (PMID 36503523, 2022). "Moreover, tumor necrosis factor (TNF)-related apoptosis-inducing ligand (TRAIL)-expressing SG NK cells control CD4+ T cell response during chronic viral infection to limit autoimmunity." (PMID 36388880, 2022). "We show here that TNF deficiency is not sufficient to induce either GC formation or pathogenic autoimmunity in Sle1 mice." (PMID 35104241, 2022). "While in murine CMV model and WNV infection model, TNFα antagonist indeed rectified cerebellar abnormalities and developmental gene expression, it has been found to augment Multiple Sclerosis phenotype in humans by increasing peripheral and CNS autoimmunity." (PMID 34858132, 2021). "Furthermore, cannabinoids can inhibit T cell autoimmunity, antigen-presenting cell function, and production of proinflammatory cytokines such as interleukin-1 and tumor necrosis factor-alpha." (PMID 33628507, 2021).
Autoimmunity (continued). "The reason why anti‐TNF induces a similar psoriatic phenotype (same subtype and localizations) only in a portion of subjects affected by different autoimmune conditions is still unknown." (PMID 31577850, 2020). "Our objective was to determine if men with autoimmune conditions are being counseled regarding the unknown reproductive effects of anti-TNF agents prior to initiation of therapy." (PMID 32718310, 2020). "For example, CD8+ T-cells are found to be more polarized than normal toward a Th1 response and production of cytokines such as IFN-gamma and TNF-alpha associated with senescence and autoimmunity, even in the absence of diagnosis of an autoimmune condition." (PMID 32566271, 2020). "Therefore, our study provides first evidence that in such cases anti-TNFα therapy should be considered to control autoimmunity while maintaining rLeptin substitution for the metabolic control of lipodystrophy." (PMID 31822667, 2019). "TNFα is a critical regulator of autoimmunity, including AIH in both patients and animal models." (PMID 31031775, 2019). "Our results now indicate that, in the setting of a pre-existing inflammatory condition, leptin therapy fuels inflammation and increases disease activity in autoimmunity via the induction of TNFα-producing cells and by metabolically priming immune cells towards a pro-inflammatory phenotype." (PMID 31822667, 2019). "The role of TNF-α in autoimmunity may vary in different diseases.Compelling evidence indicated a pathogenic role of this cytokine in RA, while a protective role has been found inSLE." (PMID 30916218, 2019). "However, some rare patients treated with these drugs paradoxically develop an aggravation of their disease or new onset autoimmunity, revealing an immunosuppressive facet of TNF." (PMID 29593717, 2018). "Neutralization of TNFα with several antagonists including mAb (infliximab, adalimumab) and a recombinant TNFα receptor fusion protein, etanercept, have been widely used to treat the autoimmunity driving RA." (PMID 30166987, 2018). "In the complex scenario of TNF- α effects in inflammation and autoimmunity one might bear in mind the role of TNF- α receptors, which genetic variability might underlies complex autoinflammatory diseases such as TRAPS." (PMID 29579081, 2018). "In addition to suppressing systemic autoimmunity, TNF can also suppress organ-specific autoimmunity." (PMID 29751683, 2018). "Defects in ZFP36 TZF increased the stability of TNF-α mRNA and subsequently caused inflammation through the overproduction of TNF-α45; therefore, defects in ZFP36 TZF can lead to a systemic inflammatory syndrome and autoimmunity in mice." (PMID 29426877, 2018). "In PsoA, anti-TNF therapy has been successful in agreement with the key role of TNF in the pathogenesis and the generation by PsoA patients of anti-TNF autoantibodies referred as “beneficial autoimmunity to pro-inflammatory mediators”." (PMID 27338143, 2016). "HTLV-1-induced changes in the activity of regulatory CD4 T-cell molecules affect the homeostasis of cytokines, including IFN- γ, TNF-α, TGF-β and IL-10, and disrupt the balance in inflammatory and anti-inflammatory responses, leading to the loss of tolerance and the development of autoimmunity." (PMID 26712781, 2015). "Moreover, vitamin D inhibits expression of Th1 cytokines, such as IL-2, interferon-γ and tumor necrosis factor-α, thus providing protection against autoimmunity." (PMID 25644263, 2015). "There was considerable evidence supporting that the minor “A” allele of TNF-α-308 could contribute the improvement of TNF-αlevel as a potent transcriptional activator, leading to increased susceptibility of inflammation and autoimmunity." (PMID 23723980, 2013).